PTPRM (protein tyrosine phosphatase receptor type M)
Diseases named in the same sentence as PTPRM in open-access papers (continued):
Sharing a sentence is not in itself a finding about the gene and the disease.
cocaine dependence (1 paper, 2012). A psychologically and socially impaired state, with or without physiological changes, that develops as a result of using cocaine and which leads to compulsive behaviors to acquire the substance. "Furthermore, four other genes, FAM38B (cocaine dependence in black women), PTPRM (marijuana dependence in black women), CSMD1 (nicotine dependence in black women), and RELN (cocaine dependence in white men), contain at least one SNP that met the SNP-based relaxed threshold of significance." (PMID 23365539, 2012).
coloboma (1 paper, 2023). An abnormality in which a part of a structure in one or both eyes is missing. "Therefore, we suggested that PTPRM could be a candidate gene for the upper eyelid coloboma trait." (PMID 38066959, 2023).
COVID-19 (1 paper, 2025). A disease caused by infection with severe acute respiratory syndrome coronavirus 2. "This suggests a potential direct relationship between PTPRM’s functionality and COVID-19, a molecular mechanism underlying the disease." (PMID 40593827, 2025).
depression (1 paper, 2024). "Of 10 GWAS studies of MDD or depression, two found an association between DOCK2 and MDD/depression, and four indicated loci in UGT8, PTPRM, or DAB1 as variants associated with MDD/depression." (PMID 39287932, 2024).
epilepsy (1 paper, 2018). A brain disorder characterized by episodes of abnormally increased neuronal discharge resulting in transient episodes of sensory or motor neurological dysfunction, or psychic dysfunction. "Moreover, PTPRM, PPFIA1, SLC1A2, and SGCE were confirmed to be associated with epilepsy, while PTPRD, ASB5, and MCU were involved in neurological disorders." (PMID 29568349, 2018).
eyelid coloboma (1 paper, 2023). "Using selective sweep analysis, we found that PTPRM on chromosome Z influences the upper eyelid coloboma phenotype of the Huoyan goose, and TYRP1 is a plausible candidate gene for the Huoyan gosling feather color." (PMID 38066959, 2023). "Therefore, our results suggested that PTPRM, a gene located on the chromosome 12 that is identified as the Z chromosome, is a strong candidate gene for the upper eyelid coloboma trait." (PMID 38066959, 2023).
lupus (1 paper, 2021). "PTPRM is a well-studied tyrosine phosphatase enzyme implicated in regulating axonal guidance and cellular adhesion; it may have complex associations with other systemic autoimmune conditions, including lupus." (PMID 35154781, 2021).
medulloblastoma (1 paper, 2020). A malignant, invasive embryonal neoplasm arising from the cerebellum. "One of these SNPs, located in 18p11.23 (PTPRM) showed suggestive evidence for an association with medulloblastoma risk also in the validation cohort." (PMID 32056145, 2020). "In the validation cohort, one genetic variant, rs78021424 (18p11.23, PTPRM), was associated with medulloblastoma risk with an OR in the same direction as in the discovery cohort." (PMID 32056145, 2020). "In the validation study, rs78021424 (18p11.23, PTPRM) was associated with medulloblastoma risk with OR in the same direction as in the discovery cohort (ORT = 1.59, pvalidation = 0.02)." (PMID 32056145, 2020). "In summary, we have identified 11 loci that may be associated with medulloblastoma development in children and young adults, including the 18p11.23 (PTPRM) loci that was validated in a separate cohort." (PMID 32056145, 2020). "The role of PTPRM in medulloblastoma is, to our knowledge, unknown, but it is interesting to note that the PTPRM protein has been shown to interact with beta-catenin." (PMID 32056145, 2020).
neuroendocrine tumor (1 paper, 2024). "Increased expression of PTPRM in small intestinal neuroendocrine tumor cells reduces cell growth and division and induces cell death." (PMID 39748948, 2024).
ovarian carcinoma (1 paper, 2023). A malignant neoplasm originating from the surface ovarian epithelium. "PTPRM expression was significantly lower in ovarian cancer compared with that in normal tissues in the GEPIA database (P < 0.05)." (PMID 37403117, 2023).
ovarian epithelial tumor (1 paper, 2023). A benign, borderline, or malignant tumor that originates from the surface epithelium of the ovary. "In this study,we aimed to detect PTPRM expression in ovarian epithelial tumors, analyze its relationship with the clinicopathological features and survival prognosis of patients with EOC, and provide a theoretical basis for new targets for EOC treatment." (PMID 37403117, 2023). "In this study, we aimed to detect the expression of PTPRM in ovarian epithelial tumors, analyze its relationship with the clinicopathological features and survival prognosis of patients with EOC, and provide a theoretical basis for new targets for EOC treatment." (PMID 37403117, 2023).
pancreatic cancer (1 paper, 2024). "We identified that PTPRM gene silencing (top 25% quartile expression vs. bottom 25%) in pancreatic cancer patients showed a significant association with poor overall survival probability (Log Rank P = < 0.05, hazard ratio [HR] = 1.82; 95% confidence interval [CI] = 0.995–4.336; P = < 0.05)." (PMID 38475971, 2024). "We identified 4 compounds, AZ960, JAK8517, JAK18709 and Ruxolitinib, that specifically target proteins in the JAK/STAT pathway and compared their drug sensitivity to PTPRM promoter methylation status in pancreatic cancer cell lines." (PMID 38475971, 2024).
pancreatic ductal adenocarcinoma (1 paper, 2023). An infiltrating adenocarcinoma that arises from the epithelial cells of the pancreas. "Sahni showed reduced plasma PTPRM in patients with a poor prognosis of pancreatic ductal adenocarcinoma, suggesting that PTPRM could be used as a new blood-based biomarker to predict the prognosis of pancreatic ductal adenocarcinoma." (PMID 37403117, 2023).
psoriasis (1 paper, 2022). An autoimmune condition characterized by red, well-delineated plaques with silvery scales that are usually on the extensor surfaces and scalp. "The integration of these interesting results with the findings of our study suggests for the first time a contribution of PTPRM to the pathogenesis of psoriasis." (PMID 36139479, 2022). "Our findings suggest for the first time a contribution of the PTPRM gene product to the pathogenesis of psoriasis." (PMID 36139479, 2022).
scoliosis (1 paper, 2025). A congenital or acquired spinal deformity characterized by lateral curvature of the spine. "Whole-exome sequencing of a French-Canadian AIS cohort with severe scoliosis identified rare variants in the PTPRM gene, which encodes Protein Tyrosine Phosphatase μ (PTPμ)." (PMID 39940812, 2025). "The small sample size of the genetic association study may have limited the ability to detect significant associations between rare variants in PTPRM and scoliosis severity." (PMID 39940812, 2025). "Whole-exome sequencing (WES) of a French-Canadian cohort, including 70 AIS females with severe scoliosis (surgical cases) and 69 age-matched healthy females as controls, revealed three rare variants (MAF < 0.01) within the PTPRM gene." (PMID 39940812, 2025). "By identifying and targeting specific genetic and molecular factors involved in the development and worsening of scoliosis, PTPRM gene emerged as a promising candidate." (PMID 39940812, 2025).
type 2 diabetes (1 paper, 2019). "This signal seems to correspond to the PTPRM gene that encodes a tyrosine phosphatase enzyme highly expressed in adipose tissues and associated with HDL cholesterol levels, body weight and type 2 diabetes." (PMID 31791255, 2019).
Upper eyelid coloboma (1 paper, 2023). A short discontinuity of the margin of the upper eyelid. "Our results indicated that the upper eyelid coloboma trait in Huoyan geese was probably generated by the effect of the PTPRM gene located on the Z chromosome." (PMID 38066959, 2023).
tumor (19 papers, 2012 to 2024). "The correlation analysis results of miR-205-5p and PTPRM with ssGSEA and tumor-associated phenotypes showed that miR-205-5p and PTPRM seemed to have a certain correlation with tumor immunity." (PMID 35712349, 2022). "PTPRM is a tumor-associated factor, and its role in cancer has been investigated in several malignancies." (PMID 35626106, 2022). "MiR-205-5p and PTPRM have good diagnostic efficacy and are expressed differently in different clinical features and are related to tumor immunity." (PMID 35712349, 2022). "PTPRM has been reported as a mutated tumour-associated factor in many cancers." (PMID 34225581, 2021). "A number of Protein Tyrosine Phosphatases (PTPs) have been described in human cancers as tumour suppressor genes and among the most studied include PTPRM;, PTPN13; and PTPRG;." (PMID 38475971, 2024). "During tumor development, PTPRM affects cell proliferation, survival, apoptosis, vesicular transport, adhesion, migration, and invasion." (PMID 37403117, 2023). "The positive PTPRM expression rate significantly decreased with age, progressing clinical stage, and tumor recurrence, and the larger the mass diameter, the higher the positive PTPRM expression rate." (PMID 37403117, 2023). "In general, miR-205-5p and PTPRM have a certain correlation with tumor immunity and global methylation, and we will further explore their role in tumor immunity in future experiments." (PMID 35712349, 2022). "After a series of bioinformatics analyses and external experimental verification, upregulated miR-205-5p and downregulated PTPRM in tumor tissues were finally screened out." (PMID 35712349, 2022). "In conclusion, miR-205-5p and PTPRM interact with DNA methylation, tumor immunity and inflammation in the tumor microenvironment." (PMID 35712349, 2022). "Second, the survival analysis showed that 7 genes had significant (p < 0.05) Kaplan–Meier curves, including 5 genes (MS4A1, N4BP2L1, IGF1R, TCF7L2 and COL11A1) based on the normal expression, and 2 genes (TCF7L1 and PTPRM) based on the tumor expression." (PMID 35406404, 2022). "In the multivariate Cox′s proportional hazards model analysis, PTPRM expression level, tumor size, LVSI, and LNM were found to be independent prognostic factors." (PMID 32826853, 2020). "Protein tyrosine phosphatase receptor type M (PTPRM) is a member of the PTP family and was reported as a tumor-associated factor which was mutated in many kinds of cancers." (PMID 32826853, 2020). "Our data showed that ectopic expression of PTPRM suppressed tumor cell growth, whereas depletion of PTPRM facilitated anchorage-independent cell growth and increased saturation density." (PMID 25910225, 2015). "The fact that we were unable to recover neomycin-resistant cell clones stably expressing PTPRM in long-term culture also agrees with its role as a tumor suppressor." (PMID 25910225, 2015). "PTPRM levels were higher in well differentiated tumours and were decreased in moderately differentiated tumours (p = 0.011) and poorly differentiated tumours (p = 0.031)." (PMID 23185569, 2012). "The results showed that patients with higher tumour grade had relatively lower levels of PTPRM expression." (PMID 23185569, 2012). "A significant decrease of PTPRM transcripts was seen in poorly differentiated and moderately differentiated tumours compared with well differentiated tumours." (PMID 23185569, 2012). "PTPRM has an important role in tumorigenesis as a tumor suppressor gene." (PMID 37403117, 2023). "Likewise, sine oculis homeobox homolog 1 (SIX1) and protein tyrosine phosphatase receptor type M (PTPRM) expressed in tumor cells both promote tumor lymphangiogenesis by inducing increased expression of VEGF-C." (PMID 37234990, 2023). "The effects of PTPRM on tumor growth and LNM were further confirmed by animal experiments." (PMID 32826853, 2020).
tumor (continued). "For this situation, we speculate that whether PTPs function as oncogenes or tumor suppressor genes is cellular context dependent and the newly discovered role of PTPRM in promoting the progression of CCa may be due to the tumor heterogeneity." (PMID 32826853, 2020). "Moreover, high PTPRM expression had a notable correlation with tumor size (P = 0.019) and LNM (P = 0.015)." (PMID 32826853, 2020). "Thus DDIAS sustains STAT3 phosphorylation by inhibiting the accessibility of PTPRM to STAT3, suggesting a novel mechanism of PTPRM as a tumor suppressor." (PMID 31900385, 2020). "As the RNA interference technique and monoclonal antibody clinical therapeutic application, nanovesicle delivery system packaged with siRNAs or other targeting PTPRM drugs might exert potential anti-tumor role in CCa treatment in the future." (PMID 32826853, 2020). "Among these, PTPRK, PTPRM, and PTPRT are implicated as tumor suppressors, raising the possibility that they may also regulate ZNRF3 in certain cell types." (PMID 31934854, 2020). "Taken together, this study demonstrates a putative tumor suppressive role for PTPRM and that genetic and epigenetic alterations of PTPRM may contribute to early step of colorectal tumorigenesis." (PMID 25910225, 2015). "The tumor suppressor role of PTPRM was demonstrated by its ability to suppress colony formation." (PMID 25910225, 2015). "Our data that PTPRM negatively regulates cell growth suggest a tumor suppressive role of PTPRM." (PMID 25910225, 2015). "Furthermore, PTPRM levels were higher in tumours of early TNM stage and decreased in the TNM2 (p = 0.032)." (PMID 23185569, 2012). "We further explored specific communication pathways and discovered that signaling via PTPRM, MIF, MK, PECAM1, and SPP1 was markedly more active in the tumor group compared to the normal group." (PMID 39165361, 2024). "The expression of PTPRM was low in patients with EOC, and the positive rate of PTPRM expression significantly decreased with progressing stages of EOC and tumor recurrence, suggesting the role of PTPRM as a tumor suppressor in the progression of EOC." (PMID 37403117, 2023). "The expression of miR-205-5p (p < 0.0001) and UBE2C (p = 0.0093) were upregulated in tumor tissues, while the expressions of miR-140-3p (p = 0.0293), PTPRM (p < 0.0001), GPD1L (p = 0.0002), and FOXF2 (p < 0.0001) were downregulated in tumor tissues." (PMID 35712349, 2022). "The deleted 18p11.21 region contains important tumor inhibitory genes, for example EPB41L3, L3MBTL4, ARHGAP28, PTPRM, and ROCK1 (for complete list of genes in deletion regions)." (PMID 22363777, 2012). "Among them, the positive expression rate of PTPRM decreased with progressing stages of EOC and tumor recurrence, and the difference was significant, indicating that PTPRM may play a role in the progression and recurrence of EOC." (PMID 37403117, 2023). "PTPRM expression was low in patients with EOC, and the PTPRM positive-expression rate significantly decreased with progressing stages of EOC and tumor recurrence, suggesting that PTPRM acts as a tumor suppressor in EOC progression." (PMID 37403117, 2023). "Aberrant methylation of PTPRM promoter was detected mainly in the tumor, as the matching non-tumor mucosal tissues only showed scattered methylation in PTPRM promoter region." (PMID 25910225, 2015). "Tumours with lymphatic involvement appeared to have lower levels of PTPRM transcripts than the node negative tumours but was not statistically significant." (PMID 23185569, 2012). "TNM3 and TNM4 tumours also tended to have decreased levels of PTPRM, compared to TNM1 tumours, but this was not statistically significant." (PMID 23185569, 2012).
cancer (16 papers, 2012 to 2026). A tumor composed of atypical neoplastic, often pleomorphic cells that invade other tissues. "Having demonstrated the presence of PTPRM promoter hypermethylation associated transcription silencing, we studied if PTPRM epigenetic loss in cancer patients had any impact on the clinical outcome in these patients." (PMID 38475971, 2024). "The involvement of PTPRM in the pathogenic development of other cancers including CRC remains to be elucidated." (PMID 25910225, 2015). "In line with previous findings that deletion of 18p is a frequent event in CRC22, our study showed recurrent loss of 18p11, where the PTPRM locus resides, in the carcinoma lesions by oligonucleotide microarray." (PMID 25910225, 2015). "PTPRM was identified as a potential diagnostic and prognostic biomarker for PC carcinomas and could represent a potential therapeutic target." (PMID 35626106, 2022). "Furthermore, our data demonstrated that low PTPRM expression is associated with poor overall survival and PTPRM methylation marks maybe used as biomarkers for JAK/STAT targeting anti-cancer drugs response." (PMID 38475971, 2024). "Additionally, the present study identified a diagnostic and prognostic biomarker for PC carcinoma, PTPRM, that could potentially be a target for the development of novel cancer therapeutics." (PMID 35626106, 2022). "In our cancer cohort, PTPRM represented the PTP with highest number of individuals with epimutations and high median expression values in healthy subjects (> 5 TPM)." (PMID 38475971, 2024). "PTPRM can activate STAT3 signaling pathway to enhance the anti-cancer immune responses and rescuing the suppressed immunologic microenvironment in tumors." (PMID 35712349, 2022). "PTPRM has a role in signal transduction, cell proliferation, and oncogenic transformation and is directly involved in numerous cancers, including breast, pancreatic, cervical, lung, and colorectal." (PMID 36011407, 2022). "Genes encoding ANPEP, PROK2, CHP2, PTPRM, AREG, and COL7A1 showed significant differential expression in SRC and PC carcinomas." (PMID 35626106, 2022). "Among genes differentially expressed between PC and SRC carcinomas, protein tyrosine phosphatase receptor type M (PTPRM) was overexpressed in PC and related to unfavorable clinical factors." (PMID 35626106, 2022). "We showed that the genes encoding ANPEP, PROK2, CHP2, PTPRM, AREG, and COL7A1 were differentially expressed between SRC and PC carcinomas." (PMID 35626106, 2022). "Then we examined the effect of PTPRM knockdown on DDIAS-knockdown–induced suppression of cancer cell growth and invasion." (PMID 31900385, 2020). "PTPRM expression has been shown to be negatively correlated with oncogenic cell growth and cancer prognosis." (PMID 32023328, 2020). "PTPRM has been shown to exhibit homophilic binding and confer cell-cell adhesion in cells including epithelial and cancer cells." (PMID 23185569, 2012). "PTPRM plays an important role in the development of a variety of malignancies." (PMID 37403117, 2023). "Protein tyrosine phosphatase receptor type M (PTPRM) is involved in cancer development and progression; however, its role in EOC remains unclear." (PMID 37403117, 2023). "The role and precise mechanism of PTPRM in cancer remain unknown, and further exploration is necessary to elucidate its role in SRC and PC carcinomas." (PMID 35626106, 2022). "Since PTPRM could influence cell migration and invasion, we further examined whether PTPRM can induce EMT of cancer cells." (PMID 32826853, 2020). "Protein tyrosine phosphatase μ (PTP μ or PTPRM) has a similar structure to cell-cell adhesion molecules and has been shown to exhibit homophilic binding and confer cell-cell adhesion in cells including epithelial and cancer cells." (PMID 23185569, 2012).